EPB41L3 (erythrocyte membrane protein band 4.1 like 3)
Description:
Tumor suppressor that inhibits cell proliferation and promotes apoptosis. Modulates the activity of protein arginine N-methyltransferases, including PRMT3 and PRMT5.
Synonyms: DAL-1; DAL1; KIAA0987; 4.1B
Tractability: Small molecule: a structure with a bound ligand is known. Antibody: UniProt places it where antibodies can reach, with high confidence; its Gene Ontology location is reachable by antibodies, with high confidence; the Human Protein Atlas places it where antibodies can reach. PROTAC: ubiquitination databases record sites on it; its protein half-life has been measured.
Gene: Protein-coding gene on chromosome 18 (5,392,379 to 5,630,700, reverse strand). Ensembl gene ENSG00000082397.
Subcellular location: Cytoplasm, cytoskeleton; Cell junction; Cell membrane; Cytoplasm
Subcellular location (Human Protein Atlas): Cell Junctions; Plasma membrane; Basal body; Primary cilium
Pathways (Reactome):
Sensory Perception: Sensory processing of sound by inner hair cells of the cochlea; Sensory processing of sound by outer hair cells of the cochlea
Neuronal System: Neurexins and neuroligins
Gene Ontology:
Molecular function: protein binding; cytoskeletal protein-membrane anchor activity; structural constituent of cytoskeleton; actin binding; cytoskeletal protein binding; structural molecule activity
Biological process: actomyosin structure organization; cortical cytoskeleton organization; myelin maintenance; neuron projection morphogenesis; paranodal junction assembly; protein localization to juxtaparanode region of axon; protein localization to paranode region of axon; protein localization to plasma membrane; regulation of cell shape; cortical actin cytoskeleton organization; regulation of neurotransmitter receptor localization to postsynaptic specialization membrane
Cellular component: cell junction; cell-cell junction; plasma membrane; axolemma; cytoskeleton; cytosol; juxtaparanode region of axon; paranode region of axon; anchoring junction; cytoplasm; glutamatergic synapse; postsynapse
Genetic constraint (gnomAD): Loss-of-function variants: 51 observed, 114.68 expected, observed/expected ratio (o/e) 0.44, 90% interval 0.35 to 0.56. The upper end of that interval is the gene's LOEUF score, 0.56, which puts it in group 2 of 6, group 1 being the genes least tolerant of losing a copy. Missense variants: 1,241 observed, 1,383.6 expected, observed/expected ratio (o/e) 0.9, 90% interval 0.86 to 0.94. Synonymous variants: 562 observed, 563.26 expected, observed/expected ratio (o/e) 1, 90% interval 0.93 to 1.07.
Homologues: Orthologues: chimpanzee EPB41L3 (99% identical), macaque EPB41L3 (99% identical), rabbit EPB41L3 (91% identical), rat Epb41l3 (88% identical), dog EPB41L3 (87% identical), pig EPB41L3 (76% identical), tropical clawed frog epb41l3 (74% identical), guinea pig EPB41L3 (71% identical), mouse Epb41l3 (61% identical), zebrafish epb41l3a (45% identical), zebrafish epb41l3b (44% identical), Caenorhabditis elegans frm-1 (32% identical), and 6 more. Paralogues in human: EPB41L2 (41% identical), EPB41L1 (39% identical), EPB41 (38% identical), EPB41L4B (19% identical), EPB41L5 (19% identical), FRMD3 (16% identical), EPB41L4A (16% identical), FRMD5 (16% identical), FRMD6 (12% identical), MYLIP (11% identical).
Diseases named in the same sentence as EPB41L3 in open-access papers:
EPB41L3 is named in the same sentence as 52 diseases in open-access papers, as found by Europe PMC text mining. Sharing a sentence is not in itself a finding about the gene and the disease. The quoted sentences say what the papers report.
lung carcinoma (18 papers, 2010 to 2025). "Previous studies implicated EPB41L3 as a tumor suppressor with reduced expression in numerous tumors including lung cancer and breast cancer." (PMID 33323539, 2020). "This is in agreement with study showing that the hypermethylation of EPB41L3/DAL1 was associated with its downregulation in lung cancer." (PMID 20698951, 2010). "Loss of the 4.1B/DAL-1 protein leads to a substantial decrease in the expression of numerous EMT markers, including E-cadherin and β-catenin in lung cancer cell lines, which agrees with our EPB41L3 knockdown data." (PMID 37373330, 2023). "In a different cancer type, non-small cell lung cancer (NSCLC), PMV-mediated transfer of miR-223 promoted tumor invasiveness of human lung cancer cells (A549) by targeting the cytoskeletal protein erythrocyte membrane protein band 4.1-like 3 (EPB41L3)." (PMID 34149456, 2021). "As the gene involved in cytoskeletal construction, EPB41L3 has also been shown to promote tumor metastasis by promoting epithelium-mesenchymal transformation in advanced lung cancer." (PMID 33898304, 2021). "Of note, platelet microvesicles effectively delivered miR-223 to lung cancer cells and promoted cancer cell invasion by reducing Erythrocyte Membrane Protein Band 4.1-like 3 (EPB41L3) levels." (PMID 33076269, 2020). "Platelet-derived MVs from lung cancer patients are also able to induce metastasis and promote tumor cell invasion by delivering miR-223 that targets tumor suppressor gene EPB41L3 (erythrocyte membrane protein band 4.1-like 3)." (PMID 32641036, 2020). "Third, exogenous miR-223 derived from platelets reduced the protein level of tumor suppressor EPB41L3 and thus promoted the lung cancer cells invasion." (PMID 25881295, 2015). "In lung cancer cells, it promotes tumor invasiveness through targeting EPB41L3." (PMID 34205829, 2021). "EPB41L3 (DAL1) binds to YWHAZ, and the YWHAZ/β-catenin axis promoted epithelial-mesenchymal transition and lung cancer metastasis." (PMID 27534621, 2016). "The previous study of PRR11 was conducted and interpreted in the setting of lung cancer and showed that PRR11-knockdown dysregulated the expression of multiple important gene in critical pathways such as cell cycle, tumorigenesis and metastasis (e.g. CCNA1, RRM1, MAP4K4 and EPB41L3)." (PMID 26252227, 2015).
gastric cancer (14 papers, 2012 to 2025). A primary or metastatic malignant neoplasm involving the stomach. "A study analysed specific CpG sites methylation and their role in the EPB41L3 expression in gastric cancer, finding a strong correlation between CpG hypermethylation and decreased EPB41L3 mRNA and protein levels." (PMID 38960143, 2024). "In gastric cancer, miR-223 promoted invasion and metastasis by targeting the tumor suppressor, EPB41L3 erythrocyte membrane protein band 4.1 like 3 (EPB41L3)." (PMID 28969027, 2017). "In keeping with this finding, a recent study demonstrated that miR-223 promoted cell motility through post-transcriptional downregulation of tumor suppressor EPB41L3 in gastric cancer cells." (PMID 22470493, 2012). "Moreover, miR-223 was revealed to promote the invasion and metastasis of gastric cancer by regulating erythrocyte membrane protein band 4.1-like 3 (EPB41L3)." (PMID 36276078, 2022). "In gastric cancer, miR-223 has been found to downregulate the expression of EPB41L3, which acts as a tumor suppressor of gastric cancer and could promote the cell migration and invasion in gastric cancer cells." (PMID 32404179, 2020). "Notably, miR-233 is highly expressed in gastric cancer and promotes cell proliferation and invasion by targeting EPB41L3; and overexpression of miR-223 was found to correlate with tumor metastasis and poor prognosis in patients with colorectal cancer and plays an oncogenic role." (PMID 27150195, 2016). "In contrast, CDH2 was downregulated in gastric cancer, while EPB41L3, DNASE2, and XPC showed no significant expression differences between gastric cancer and normal tissues." (PMID 40393971, 2025). "Study in metastatic gastric cancer cells has found that miR-223, under the induction of Twist, down-regulates the expression of the key target gene EPB41L3 by directly targeting its 3′-non-translation region, enhancing the metastasis of cancer cells." (PMID 32670359, 2020). "It is apparent that OS is different from other tumors in which high levels of EPB41L3 inhibits tumor progression and predicts a favorable prognosis, such as esophageal squamous cell carcinoma (ESCC) and gastric cancer (GC)." (PMID 33323539, 2020).
breast carcinoma (10 papers, 2006 to 2023). "Our EPB41L3/DAL1 expression data showed that its downregulation could be associated with an increased risk of relapse in patients with high risk breast cancer." (PMID 20698951, 2010). "Inactivation of the erythrocyte membrane protein band 4.1-like 3 (EPB41L3) gene through methylation is involved in breast cancer and renal clear cell carcinoma." (PMID 34205890, 2021). "In another study, inactivation of the EPB41L3 gene through methylation was involved in breast cancer and renal clear cell carcinoma." (PMID 34205890, 2021). "The expression of EPB41L3 was greatly reduced in many kinds of tumors, including non-small cell lung cancer, meningiomas, breast cancer, renal clear cell carcinoma, and ovarian cancer." (PMID 25050929, 2014). "The EPB41L3/DAL1 protein suppresses the growth of MCF7 breast cancer cells and increases attachment of these cells to a variety of extracellular matrices." (PMID 20698951, 2010). "EPB41L3 has been regarded as a tumor suppressor that inhibits the progression and development of several types of cancer, including lung adenocarcinoma, meningioma, breast cancer, ovarian cancer, and prostate cancer." (PMID 37373330, 2023).
meningioma (10 papers, 2009 to 2023). A generally slow growing tumor attached to the dura mater. "EPB41L3 is potentially a critical growth regulator in meningioma pathogenesis and is normally expressed at high levels in brain, with lower levels in kidney, intestine, and testis." (PMID 19804644, 2009). "Another pivotal player in meningioma’s development is EPB41L3, also known as DAL-1 or 4.1B, a tumor-suppressor gene that encodes erythrocyte membrane protein-band 4.1-like 3, involved in cell–cell interaction and having an important role in the control of motility." (PMID 38137885, 2023).
Adenocarcinoma of the Lung (7 papers, 2006 to 2023). "The EPB41L3 gene (DAL-1/4.1B: differentially expressed in adenocarcinoma of the lung) is located in the 18p11.3 region and codes for an adhesion protein belonging to the 4.1 family of membrane-associated proteins, which is strongly expressed in the brain and also regulates cell growth." (PMID 25621889, 2015).
non-small cell lung carcinoma (6 papers, 2014 to 2023). A group of at least three distinct histological types of lung cancer, including non-small cell squamous cell carcinoma, adenocarcinoma, and large cell carcinoma. "The high miR-223 levels in platelet-secreted EVs from non-small-cell lung carcinoma (NSCLC) patients reduce the protein level of the tumor suppressor EPB41L3, promoting lung cancer cell invasion." (PMID 33869035, 2021).
prostate carcinoma (6 papers, 2007 to 2023). A carcinoma that arises from epithelial cells of the prostate gland. "The downregulation of EPB41L3 expression may therefore largely reflect the loss of basal cells during prostate cancer development." (PMID 20860828, 2010). "We have previously reported downregulation of EPB41L3 encoding protein band 4.1B and upregulation of EPB41L4B encoding EHM2, respectively, in prostate cancer, in accord with observations by other groups." (PMID 20860828, 2010). "The 4.1B protein is downregulated in several carcinomas, including prostate cancer, likely by deletion or promoter hypermethylation of the EPB41L3 gene promoter." (PMID 20860828, 2010). "We report here that hypermethylation of EPB41L3 is also prevalent in prostate cancer." (PMID 17280610, 2007). "Previous studies have concurrently reported changes in the expression of EPB41L3/4.1B and EPB41L4B/EHM2 in many prostate cancers." (PMID 20860828, 2010). "Real-time RT-PCR revealed GADD45A, MX1, EPB41L3/DAL1, and FBLN1 as generally downregulated in prostate cancer, whereas HOXB13 and EPB41L4B were upregulated." (PMID 17280610, 2007). "The analysis of individual genes by quantitative real-time PCR revealed that many (e.g. MX1, EPB41L3), but not all (notably BCCIP and TLR3) of the genes significant in the interaction analysis were also overexpressed generally in prostate cancers compared to benign tissues." (PMID 17280610, 2007).
cervical cancer (5 papers, 2015 to 2024). A primary or metastatic malignant neoplasm involving the cervix. "Recently an integrated bioinformatics approach identified that EPB41L3 was hypermethylated and correlated with a decreased expression of EPB41L3 mRNA in cervical cancer tissues compared with normal tissues." (PMID 38960143, 2024). "It was well reported that EPB41L3 plays vital role in the progression of cervical cancer and oropharyngeal cancer." (PMID 35075362, 2022). "Furthermore, miR-223 mimic or downregulation of EPB41L3 functionally reversed the effects of upregulation of HDAC10 upon the cervical cancer cells, including the cell viability, colony-forming ability, apoptosis, cell migration, and cell invasion." (PMID 35075362, 2022). "The results indicated that the expression level of EPB41L3 was low in cervical cancer." (PMID 35075362, 2022). "The study clarifies that HDAC10 inhibits cervical cancer by downregulating miR-223 and subsequently targeting EPB41L3 expression, which might provide a new insight for management upon cervical cancer and precancer lesions." (PMID 35075362, 2022). "In conclusion, the results indicated that miR-223 targets and binds to EPB41L3 in cervical cancer." (PMID 35075362, 2022). "However, how the crosstalk network of HDAC10, miR-223, and EPB41L3 regulates the progression of cervical cancer is still unclear." (PMID 35075362, 2022). "Thus, EPB41L3 plays a vital role in regulating the pathophysiological process of cervical carcinoma." (PMID 35075362, 2022). "Various host cell methylated genes such as SOX1, PAX1, JAM3, EPB41L3, CADM1, and MAL have been investigated for predicting cervical lesions, with PAX1 gene methylation showing the most significant correlation with the progression of cervical intraepithelial neoplasia and cervical cancer occurrence." (PMID 39155349, 2024).
esophageal squamous cell carcinoma (3 papers, 2015 to 2021). Esophageal squamous cell carcinoma (ESCC) is a type of esophageal carcinoma (EC) that can affect any part of the esophagus, but is usually located in the upper or middle third. "In the case of esophageal squamous cell carcinoma (ESCC), a cancerous tumor, EPB41L3 expression is reduced." (PMID 34205890, 2021).
atherosclerosis (2 papers, 2018). A disease characterized by the build-up of fatty material and calcium deposition in the arterial wall resulting in partial or complete occlusion of the arterial lumen. "miR-223 controls erythrocyte membrane protein band 4.1 like 3 (EPB41L3) gene, known to be associated with atherosclerosis." (PMID 30170601, 2018).
hepatocellular carcinoma (2 papers, 2018 to 2020). A malignant tumor that arises from hepatocytes. "For example, LINC00052 increases EPB41L3 to repress hepatocellular carcinoma migration and invasion by binding miR-452-5p." (PMID 33231561, 2020).
Azoospermia (1 paper, 2023). Absence of any measurable level of sperm,whereby spermatozoa cannot be observed even after centrifugation of the semen pellet. "In this study, we identified four genes, GLO1, GPR135, DYNLL2, and EPB41L3 that were strongly associated with azoospermia and COVID-19." (PMID 37283758, 2023). "Nevertheless, additional studies are necessary to investigate whether EPB41L3/DAL-1 can serve as a reliable diagnostic biomarker with high sensitivity and specificity for azoospermia and COVID-19." (PMID 37283758, 2023). "The expression levels of GPR135 in azoospermia tissues positively correlated with the levels of “DYNLL2” and “EPB41L3” and negatively correlated with GLO1 expression." (PMID 37283758, 2023).
Obesity (1 paper, 2016). Accumulation of substantial excess body fat. "miR-223 has been reported to associate with various types of diseases such as cancers, obesity, rheumatoid arthritis (RA) or cardiovascular diseases, via targeting tumour suppressor EPB41L3, targeting HSP90B1 or targeting cardiac troponin I-interacting kinase." (PMID 26893485, 2016).
oligodendroglial tumor (1 paper, 2015). Oligodendrogliomas are cerebral tumors that are differentiated from other gliomas on the basis of their unique genetic characteristics and better response to chemotherapy. "In astrocytic and oligodendroglial tumors, EPB41L3 hypermethylation was a prognostic factor of poor survival (p = 0.035), and TSP-1 hypermethylation is a strong prognostic factor in oligodendroglioma, associated with prolonged survival (p = 0.003)." (PMID 25621889, 2015).
osteosarcoma (1 paper, 2020). A usually aggressive malignant bone-forming mesenchymal neoplasm, predominantly affecting adolescents and young adults. "Collectively, our study has first established the complex and vital roles of EPB41L3 and implicated EPB41L3 as a potential biomarker in osteosarcoma." (PMID 33323539, 2020). "Our findings provide mechanistic insights into the dual roles of EPB41L3 in osteosarcoma development and progression." (PMID 33323539, 2020). "In the present study, we find the upregulation of EPB41L3 expression in a large cohort of human osteosarcoma tissues and cancer cell lines." (PMID 33323539, 2020). "At the same time, we analyzed EPB41L3 expression levels in 52 specimens including 11 normal bone tissues and 41 osteosarcoma tissues by immunohistochemistry." (PMID 33323539, 2020). "In this study, through analyzing expression profiling retrieved from the Gene Expression Omnibus (GEO) dataset, we find that EPB41L3 is upregulated in primary osteosarcoma (OS) and osteosarcoma cell lines." (PMID 33323539, 2020). "A key to understanding the role of EPB41L3 in osteosarcoma will be through its regulated genes." (PMID 33323539, 2020). "Together, these results also implied oncogenic functions of EPB41L3 in osteosarcoma cells." (PMID 33323539, 2020). "Consistently, enhanced EPB41L3 expression was also observed in osteosarcoma tissues (versus OBs in GSE14359, fold change=2.5845, p=0.0032; versus OBs in GSE12865, fold change=3.6075, p=0.0001) and osteosarcoma lung metastasis tissues (versus OBs in GSE14359, fold change=2.0996, p=0.0172)." (PMID 33323539, 2020). "As far as we know, there is no clarity regarding the involvement of EPB41L3 in osteosarcoma, especially the EMT process, and the role of EPB41L3 in osteosarcoma remains to be explored." (PMID 33323539, 2020).
pancreatic cancer (1 paper, 2020). "Pancreatic cancer patients with a high expression of MAPT, EPB41L3, LOC100128977, and LOC100130148 had an evidently higher overall survival as compared with those with a low expression of MAPT (p = 0.0034), EPB41L3 (p = 0.0088), LOC100128977 (p = 0.0077), and LOC100130148 (p = 0.0017)." (PMID 33424927, 2020). "It suggested that the eight markers: MAPT, SIX3, MIR663, EPB41L3, FAM150A, TRIM73, LOC100128977, and LOC100130148 may serve as potential biomarkers for the early diagnosis of pancreatic cancer." (PMID 33424927, 2020). "However, the multivariate Cox regression analysis indicated that TRIM73, FAM150A, EPB41L3, SIX3, MAPT, LOC100128977, and LOC100130148 might not be independent factors for the prognosis of pancreatic cancer patients." (PMID 33424927, 2020).
parathyroid adenomas (1 paper, 2023). "It is possible that EPB41L3 upregulation in the Def-T subset of parathyroid adenomas reflects a self-limiting protective mechanism similar to that seen with other tumor suppressor gene pathways in early-stage neoplasms." (PMID 36992820, 2023).
ZIKV infection (1 paper, 2025). "Since AIS and nodes of Ranvier are essential for action potential initiation and propagation, it is conceivable that the simultaneous reduction of Ank3, Sptbn1, and Epb41l3 due to ZIKV infection can alter functions and structures of these excitable axonal domains." (PMID 39848964, 2025).